ENSG00000200897
Synonyms: LOC124900324
Gene: Small nucleolar RNA gene on chromosome 12 (107,374,747 to 107,374,827, forward strand). Ensembl gene ENSG00000200897.
Gene Ontology:
Biological process: RNA processing
Cellular component: nucleolus
Homologues: Paralogues in human: SNORD74B (65% identical).